MT1G (metallothionein 1G)
Diseases named in the same sentence as MT1G in open-access papers (continued):
Sharing a sentence is not in itself a finding about the gene and the disease.
osteosarcoma (4 papers, 2023 to 2025). A usually aggressive malignant bone-forming mesenchymal neoplasm, predominantly affecting adolescents and young adults. "In contrast, the anti-apoptotic gene BCL2 and metallothionein family (MT 1G and 1L) were upregulated in high-grade osteosarcoma according to work using different genetic analysis methodologies." (PMID 37107591, 2023). "Metallothionein 1G (MT1G) regulates the cell’s antioxidant status and metal ion balance, influencing the proliferation and differentiation of MSCs, thereby affecting bone regeneration and repair processes, MT1G has been verified as a target for osteosarcoma." (PMID 40276505, 2025). "Among these isoforms, MT1G, a newly identified member of the MT1 family in humans, has been linked to ferroptosis in various cancers, including colorectal cancer, hepatocellular carcinoma (HCC), esophageal adenocarcinoma, prostate cancer, pancreatic adenocarcinoma, glioblastoma, and osteosarcoma." (PMID 38906969, 2024).
pancreatic cancer (4 papers, 2021 to 2024). "The downregulation of MT1G, caused by hypermethylation of its promoter, is associated with the maintenance of pancreatic cancer stemness." (PMID 38169461, 2024). "Research has shown that MT1G plays a crucial role as a tumor suppressor in pancreatic cancer stem cells." (PMID 38169461, 2024). "The co-expressed genes of the NT5DC family, including UGT2B7, MT1G, ACADL, MT1H, and others, were found to be associated with pancreatic cancer in previous studies 37-40." (PMID 37576396, 2023). "Taken together, these results indicate that the downregulation of MT1G in gemcitabine resistant pancreatic cancer cells is related with cancer stemness features." (PMID 33537082, 2021). "Our results demonstrate that MT1G plays a tumor suppressor role in pancreatic cancer stem cells supported by the following facts: 1) MT1G expression was lower in PDAC stem cells than in bulk PDAC cells." (PMID 33537082, 2021). "Our data demonstrate that MT1G promotes the degradation of NF-κB p65 subunit via tumor necrosis factor receptor-associated factor 7 (TRAF7), thus limiting activin A secretion and suppressing pancreatic cancer cell stemness." (PMID 33537082, 2021).
renal carcinoma (4 papers, 2016 to 2024). A carcinoma arising from the epithelium of the renal parenchyma or the renal pelvis. "Three genes (SLC7A11, HMOX1, and MT1G) were identified as differentially expressed genes (DEGs) associated with renal cancer prognosis using survival analysis screening." (PMID 38609844, 2024). "In our study, we observed a significant decrease in MT1G expression in ccRCC cells compared to adjacent normal renal cells, making it a promising diagnostic marker to distinguish renal cancer from normal tissue." (PMID 38906969, 2024). "Targeted lipidomics analysis showed that 27.79% of lipids in renal cancer cells were fatty acids, and MT1G overexpression cell lines significantly promoted the total amount of fatty acids." (PMID 38906969, 2024). "SLC7A11 and HMOX1 were found to be upregulated in renal cancer tissues, while MT1G was downregulated." (PMID 38609844, 2024). "In summary, we systematically addressed the prognostic ability of SLC7A11, HMOX1, and MT1G in overall renal cancer and different renal cancer subtypes in this study." (PMID 35360452, 2021). "The survival analysis screening resulted in three DEGs associated with renal cancer prognosis, namely SLC7A11, HMOX1, and MT1G." (PMID 35360452, 2021). "Survival analysis was performed on the whole renal cancer samples in TCGA, and high expression of SLC7A11, HMOX1 and MT1G all presented some prognostic risk." (PMID 35360452, 2021). "Specifically, SLC7A11 and HMOX1 were upregulated in renal cancer tissues, while MT1G was downregulated." (PMID 35360452, 2021). "In vivo, MT1G overexpression accelerated renal cancer tumor growth and metastasis." (PMID 38906969, 2024). "By inhibiting FAO, MT1G promotes the progression of renal cancer." (PMID 38906969, 2024). "We performed ORO staining to investigate whether lipid droplets accumulated in renal cancer cells due to MT1G expression." (PMID 38906969, 2024). "While MT1G has been reported to promote sorafenib resistance in HCC cells, its role in renal cancer remained unexplored." (PMID 38906969, 2024). "Among these genes, INHBA, MT1G and SPINT2 were reported to have tumor suppressive functions in renal cancers." (PMID 26551931, 2016). "Moreover, a detectable liver metastatic nodules was found in orthotopic renal carcinoma model mice with MT1G overexpression, whereas it was not be found in control group." (PMID 38906969, 2024).
COVID-19 (3 papers, 2020 to 2024). A disease caused by infection with severe acute respiratory syndrome coronavirus 2. "Among the significantly up- or down-regulated proteins in COVID-19 patient urine, metallothionein-1G, lipoprotein lipase, β2M, PRKACA, FOLR2, and APOA4, showed significant changes compared to both healthy controls and non-COVID-19 pneumonia cases." (PMID 33203833, 2020). "Furthermore, marker genes for the MT1G-high non-alveolar macrophage Cluster 3 and the RGS1-high Cluster 6 matched those identified in BAL fluid of healthy controls and patients with COVID-19, while the SERPINB2-high Cluster 13 matched marker genes from BAL cells obtained in healthy and COPD lungs." (PMID 38132091, 2023).
gastric cancer (3 papers, 2022 to 2023). A primary or metastatic malignant neoplasm involving the stomach. "MT1G can inhibit cell growth and the cell cycle through the PI3K/AKT signaling pathway in gastric cancer cells, as the overexpression of MT1G inhibits cell proliferation, foci formation, and cell invasion and negatively regulates p-AKT." (PMID 38068944, 2023). "MT1G, as a member of MTs family, has been revealed to exert crucial role in tumorigenesis, including gastric cancer." (PMID 35167648, 2022). "Metallothionein 1G (MT1G) is a member of the metallothionein family (MTs), and hypermethylation of MT1G occurred in a variety of cancers, including gastric cancer." (PMID 35167648, 2022). "Compared with normal gastric cell GES-1, MT1G was low-expressed in gastric cancer cells (NCI-N87, HGC-27, SNU-1 and HS-746T)." (PMID 35167648, 2022). "MT1G inhibits the growth and epithelial-mesenchymal transition of gastric cancer cells by regulating the PI3K/AKT signaling pathway." (PMID 35167648, 2022). "At the same time, analysis of ferroptosis-related genes associated normal tissue and gastric cancer tissues screened out 19 FerDEGs: ten of them, i.e., TLR4, KRAS, HSF1, was highly expressed and nine of them, i.e., MUC1, PROM2, MT1G, were lowly expressed in tumor tissues." (PMID 36936437, 2023). "However, there are few reports about the role of MT1G in gastric cancer, and its mechanism is unclear." (PMID 35167648, 2022). "In addition, Wu etc. analyzed the DNA chip expression data of GEO database GSE26942, GSE33335, GSE63089 and GSE79973 and found that MT1G is low-expressed in gastric cancer." (PMID 35167648, 2022). "We speculated that the low expression of MT1G in gastric cancer maybe also related to the methylation modification, which needs further investigation." (PMID 35167648, 2022). "We speculated that MT1G may have the same function in gastric cancer cells." (PMID 35167648, 2022). "In summary, our study reveals that MT1G exerts crucial role in regulating of cell proliferation and migration of gastric cancer, providing new insights for MT1G-related pathogenesis and a basis for developing new strategies for treatment of GC." (PMID 35167648, 2022). "Further study is needed to measure how MT1G regulates cell growth and EMT process via PI3K/AKT signal pathway in gastric cancer." (PMID 35167648, 2022).
hepatoblastoma (3 papers, 2015 to 2022). Hepatoblastoma (HB) is a malignant hepatic tumor and is the most common pediatric liver cancer. "As a result, aberrant DNA methylation at the APC, CDH1, MT1G, RASSF1A and SOCS1 promoters were reported in hepatoblastoma." (PMID 36212481, 2022). "The methylation-mediated repression of MT1G has already been described in HCC and hepatoblastoma in children." (PMID 25945129, 2015).
Alzheimer disease (2 papers, 2020 to 2023). A progressive, neurodegenerative disease characterized by loss of function and death of nerve cells in several areas of the brain leading to loss of cognitive function such as memory and language. "Mathys and colleagues investigated the frontal cortex of human late onset Alzheimer disease using snRNAseq and showed expression of MT2A, MT1G, and MT1E in astrocytic cluster Ast1." (PMID 32070434, 2020).
cervical cancer (2 papers, 2015 to 2021). A primary or metastatic malignant neoplasm involving the cervix. "It was reported that MT1G, NMES1, RRAD, SFRP1, SPARC and TFPI2 were more often methylated in invasive cervical cancer samples than in normal ones, suggesting that these 6 genes may be potential tumor suppressor candidate for cervical cancer." (PMID 26329329, 2015).
colon cancer (2 papers, 2015 to 2022).
colorectal tumor (2 papers, 2019 to 2023). "The MT1G promoter is hypermethylated in colorectal tumor tissues and CRC cells." (PMID 38068944, 2023).
disc degeneration (2 papers, 2022 to 2024). "Given MT1G’s role in resisting oxidative stress and regulating metal ion balance, enhancing its expression or function could provide protection against disc degeneration." (PMID 39351146, 2024). "Chondrocytes 2 expressing MGP, MT1G, and GPX3 may play a role in reversing calcification and degeneration, and chondrocytes 4 expressing PTGES, TREM1, and TIMP1 may play a role in disc degeneration pain and inflammation." (PMID 35874809, 2022).
glioma (2 papers, 2023 to 2025). A benign or malignant brain and spinal cord tumor that arises from glial cells (astrocytes, oligodendrocytes, ependymal cells). "The five glioma subpopulations were as follows: C0 CHCHD2P9+ glioma cells (2,821 cells), C1 MALT1+ glioma cells (2,124 cells), C2 MT1G+ glioma cells (1,614 cells), C3 SOX4+ glioma cells (1,575 cells), and C4 ISG15+ glioma cells (128 cells)." (PMID 40630954, 2025).
lymph node metastasis (2 papers, 2013 to 2022). "In the present study, promoter methylation of MT1G was shown to increase the risk of lymph node metastasis in PTC patients." (PMID 24098937, 2013). "In the present study, we found that MT1G hypermethylation was an independent risk factor for lymph node metastasis in PTC." (PMID 24098937, 2013). "In the present study, our data indicated that MT1G hypermethylation was frequently found in PTC and significantly associated with lymph node metastasis." (PMID 24098937, 2013). "Similar to univariate analysis, after adjustment, MT1G hypermethylation remained significantly positively associated with lymph node metastasis (OR=2.40, 95% CI=1.19-4.83), suggesting that MT1G hypermethylation might be an independent factor in predicting lymph node metastasis for PTC patients." (PMID 24098937, 2013).
Obesity (2 papers, 2021 to 2024). Accumulation of substantial excess body fat. "Notably, analysis of the UCLAN database demonstrated a correlation between MT1G expression in ccRCC tissue and the obesity level of ccRCC patients." (PMID 38906969, 2024). "However, noteworthy, evidence has shown downregulation of MT1X and MT1G expression in lymphoblastoid cells of male subjects with non-syndromic obesity in comparison to lean subjects." (PMID 33652748, 2021).
pancreatic adenocarcinoma (2 papers, 2016 to 2024). "Sorafenib was found to induce a robust increase in the levels of the mRNA encoding MT1G in the human cell lines Hep3B and BxPC3 established from HCC and Pancreatic adenocarcinoma, respectively." (PMID 27184800, 2016).
renal tumors (2 papers, 2024). "SLC7A11, HMOX1, and MT1G were the 3 FRGs associated with the prognosis of adrenocortical carcinoma (ACC), KICH, KIRC and KIRP, while the SLC7A11 is a prognostic risk factor for above 4 different renal tumors, and high expression of MT1G increases the prognostic risk of ACC, ccRCC and chRCC." (PMID 39399506, 2024). "Analysis of survival ratio showed that renal tumors mice in situ with MT1G overexpression died more than control OENC group." (PMID 38906969, 2024). "In vivo, our subcutaneous neoplasia experiments in NVSG and nude mice consistently showed that MT1G overexpression enhanced kidney tumor growth." (PMID 38906969, 2024).
viral infection (2 papers, 2020). "The top-scoring genes in the network include the members of Interferon Induced Transmembrane Proteins (IFITM1 and IFITM3) followed by MT1E, MT1X, and MT1G and OASL, all essential proteins involved in the innate immune response to viral infection." (PMID 32012164, 2020). "In relevance to viral infection, MT1F, MT1G, and MT1H proteins exerted some amount of antiviral activity against Hepatitis C viruses (HCV), while HOXA10 was shown to suppress Hepatitis B viruses (HBV) replication." (PMID 32841292, 2020).
acute promyelocytic leukemia (1 paper, 2014). An aggressive form of acute myeloid leukemia (AML), characterized by arrest of leukocyte differentiation at the promyelocyte stage, due to a specific chromosomal translocation t(15;17) in myeloid cells. "To clarify this, we established MT1G-overexpressing acute promyelocytic leukemia NB4 (NB4MTOE) cells, and investigated whether MT1G functionally contributes to all-trans retinoic acid (ATRA)-induced NB4 cell differentiation." (PMID 25072246, 2014).
age-related macular degeneration (1 paper, 2025). Age-related loss of vision in the central portion of the retina (macula), secondary to retinal degeneration. "We analysed the expression of MT1G, AKAP12 and MAFF in postmortem human retinas with documented age-related macular degeneration (AMD) with geographic atrophy and diabetic retinopathy (DR)." (PMID 40499265, 2025).
aneurysm (1 paper, 2024). Bulging or ballooning in an area of an artery secondary to arterial wall weakening. "Nevertheless, MT1G and DDIT4 give rise to further thinking about the pathogenesis of ruptured aneurysms." (PMID 38728466, 2024).
atherosclerosis (1 paper, 2022). A disease characterized by the build-up of fatty material and calcium deposition in the arterial wall resulting in partial or complete occlusion of the arterial lumen. "Combination of IH and epinephrine induced MT1G (Metallothionein 1G), which has been shown to be highly expressed in ECs from parts of aorta (i.e., aortic arch) where atherosclerosis is more likely to occur." (PMID 36229484, 2022).
diabetic retinopathy (1 paper, 2025). "Notably, in diseased human maculas (AMD and diabetic retinopathy samples) we observed elevated MT1G, AKAP12, and MAFF in Müller glia at the margins, suggesting that macular Müller cells can activate these pathways, but perhaps only in the face of significant stress or damage." (PMID 40499265, 2025).
geographic atrophy (1 paper, 2025). "Notably, MT1G exhibited unusually strong staining in the outer nuclear layer (ONL), particularly in the areas of geographic atrophy in the retina with AMD." (PMID 40499265, 2025).
HIV-1 infection (1 paper, 2012). The type species of lentivirus and the etiologic agent of acquired immunodeficiency syndrome (AIDS). "The MT1G gene also has a role in HIV-1 infection because it upregulates MT1G expression in immature dendritic cells, which in turn facilitates the expansion of HIV-1 infection." (PMID 23236293, 2012).
large-cell lung carcinoma (1 paper, 2022). "Furthermore, MT1G was enriched in the most aggressive large-cell lung carcinoma, and high expression of MT1G correlated with poor prognostic values ​​in 24 lung large-cell lung carcinomas." (PMID 35354498, 2022).
metastatic tumour (1 paper, 2016). "Six genes were associated with tumour pathologic PT and tumour stage; among these, high expression of INTS8 and UBAP2L, and low expression of ACSM3, FCN2, LCAT, and MT1G, was significantly associated with metastatic tumour and late stage (P ≤ 0.05)." (PMID 27567667, 2016).
osteoporosis (1 paper, 2024). A condition of reduced bone mass, with decreased cortical thickness and a decrease in the number and size of the trabeculae of cancellous bone (but normal chemical composition), resulting in increased fracture incidence. "After the non-SDEGs added by GeneMANIA to establish the PPI network removed, six up-regulated SDEGs (HIST1H3G, HIST1H2BO, PTP4A1, FAM46A, MT1G and TNFSF9) and one down-regulated SDEG (PMAIP1) were identified as potential hub genes in the pathogenesis of osteoporosis." (PMID 38372699, 2024).
ovarian carcinoma (1 paper, 2022). A malignant neoplasm originating from the surface ovarian epithelium. "In addition, through the literature review, we found that except CYBB, VDAC2, IDH1, MT1G, SLC1A4, PCK2, SLC3A2, the prognostic value of other FRGs in ovarian cancer has been reported, which provided a possibility for constructing a prognostic model." (PMID 36386203, 2022).
psoriasis (1 paper, 2022). An autoimmune condition characterized by red, well-delineated plaques with silvery scales that are usually on the extensor surfaces and scalp. "Psoriasis skin-derived S.B cells expressed GPX4, FTL, and FTH1 at high levels, whereas control skin-derived S.G & S.S cells expressed high levels of GPX4, FTH1, NR4A1, NFE2L2, and MT1G." (PMID 35962439, 2022).
renal cell carcinoma (1 paper, 2024). "Even though the role of MTs in ferroptosis is not fully understood, one of its subtypes – MT-1G – was found to negatively regulate ferroptosis in hepatocellular and renal cell carcinomas and to facilitate resistance to sorafenib treatment." (PMID 39341589, 2024).
schizophrenia (1 paper, 2017). A major psychotic disorder characterized by abnormalities in the perception or expression of reality. "The paralogous genes of GBP1, MT2A and APOL1, including GBP2, MT1G, MT1E, MT1F, MT1L and APOLD1, were also upregulated in the schizophrenia cases." (PMID 28809853, 2017).
thyroid (1 paper, 2013). "MT1G contributes to suppression of thyroid carcinogenesis by inhibiting cell growth and invasiveness, and inducing cell cycle arrest and apoptosis mainly through modulating the PI3K/Akt signaling pathway and partially through regulating the Rb/E2F pathway." (PMID 24098937, 2013). "We have for the first time revealed that MT1G appears to be functional tumor suppressor involved in thyroid carcinogenesis mainly through modulating the phosphatidylinositol-3-kinase (PI3K)/Akt pathway and partially through regulating the activity of Rb/E2F pathway in this study." (PMID 24098937, 2013). "Down-regulation or silencing of MT1G might abolish tumor suppression so as to contribute to thyroid tumorigenesis." (PMID 24098937, 2013). "Thus, we speculated that other epigenetic mechanisms such as histone modification, along with DNA methylation, may contribute to MT1G inactivation in thyroid carcinogenesis." (PMID 24098937, 2013). "However, the role of MT1G in thyroid carcinogenesis remains unclear." (PMID 24098937, 2013).